IL1R2 (interleukin 1 receptor type 2)
Diseases named in the same sentence as IL1R2 in open-access papers (continued):
Sharing a sentence is not in itself a finding about the gene and the disease.
tumor (continued). "Furthermore, cluster 1 exhibited increased expression of IL1R2 and the IL-33 receptor ST2 (IL1RL1), which enhances the proportion and suppressive potential of tumor-infiltrating Treg in HNSCC patients." (PMID 33602930, 2021). "Interestingly, the most abundant cytokine–receptor pair interaction between TAMs and tumor cells was predicted for IL1B and its decoy receptor IL1R2, suggesting the inhibition of IL1B-mediated proinflammatory signaling by tumor cells." (PMID 33277616, 2020). "Expression of IL-1R2 seems to be one of the „road blocks” employed by HRS cells to interfere with normal immune functions of the surrounding lymphocytes and to counteract IL-1 action on the tumor cells themselves." (PMID 26406983, 2015). "Besides, the decoy IL-1 receptor IL-1R2 was also found highly expressed in HRS cells and may contribute to tumor-induced immune escape mechanisms by inhibition of IL-1 signal transduction." (PMID 36230815, 2022). "Results from this study suggested that patients with CRC may harbor tumor-infiltrating Tregs with a specific protein signature, including the co-stimulatory molecules (OX40, 4-1BB), cytokine receptors (IL1R2, IL21R, CCR8, CD30), and co-inhibitory molecules (PD-L1, TIGIT)." (PMID 33527196, 2021).
cancer (40 papers, 2011 to 2025). A tumor composed of atypical neoplastic, often pleomorphic cells that invade other tissues. "Collectively, these results suggest that IL-1R2 expression is associated with specific Treg cell clusters, representing differential maturation or activation states, developed in pathological conditions, in particular in cancer." (PMID 35211118, 2022). "In particular, functional studies are needed to address whether IL-1R2 is part of a signature associated with immunosuppression as suggested by data on Tregs, or whether its induction reflects cancer-related inflammation, thus explaining the link with poor prognosis." (PMID 35211118, 2022). "Expressed on neutrophils and monocytes, IL-1R2 is modulated by anti-inflammatory stimuli and plays a critical role in controlling inflammation in infections, autoimmune diseases, and cancer." (PMID 41415279, 2025). "Interleukin-1 receptor type II (IL-1R2), acting as a negative regulator of the IL-1 system, plays a key role in various inflammatory diseases and cancers." (PMID 41417784, 2025). "The overexpression of IL1R2 reverses G1 phase inhibition and cell cycle arrest, promoting cancer cell proliferation, migration, and invasion." (PMID 37728418, 2023). "Whole transcriptome analysis revealed a strong correlation of cancer cell adaption with increased interleukin 1 receptor type 2 (IL1R2) expression." (PMID 37460712, 2023). "Interleukin-1 receptor type II (IL-1R2), as a negative regulator of the IL-1 system, plays a key role in many inflammatory diseases and cancers." (PMID 38015717, 2023). "Porphyromonas gingivalis infection, which is associated with oral squamous cell carcinoma (OSCC), influenced myeloid polarization favoring the “M2”-like phenotype in macrophages and the upregulation of IL-1R2 and protumor molecules in cancer cells." (PMID 35211118, 2022). "We found that IL-1R2 mRNA levels washigher in GC tissues than in para-cancer tissues, and that the level of IL-1R2 mRNAin most GC cells was higher than that in GES1 control cells." (PMID 33704402, 2021). "IL-1R2 mRNA expression in the GC and para-cancer tissues of ninepatients with GC was measured by RT-PCR." (PMID 33704402, 2021). "IL-1R2 is expressed in a variety of diseases and tumors, and plays a role inpromoting cancer in most tumors." (PMID 33704402, 2021). "The expression of intracellular IL-1R2 in humancolorectal cancer cells is higher than that in normal colon cells." (PMID 33704402, 2021). "Targeting IL1R2 with its neutralizing antibody inhibits the self‐renewal of BTICs, breast tumorigenesis, and cancer resistance to docetaxel." (PMID 31921558, 2020). "However, in our scRNA-seq analysis, IL1B/IL1R2 were scarcely expressed outside of TANs, including in cancer cells, suggesting that IL1B-mediated cancer progression is likely driven through TANs." (PMID 41228323, 2025). "In cancer, IL-1R2 can promote a state of immune tolerance by dampening IL-1 signaling." (PMID 41415279, 2025). "CRTAC1, HRG, and IL1R2 are not cancer‐specific biomarkers, but they are broadly associated with various diseases." (PMID 40517318, 2025). "Another study even proposed that IL1R2 protects cancer cells from apoptosis." (PMID 38986222, 2024). "However, we observed MO IL-1R2 upmodulation concomitant to MO HLA-DR downmodulation in two infected febrile patients who also had advanced cancers, thus supporting the efficiency of this FC assay in stratifying the risk of infected patients." (PMID 39519183, 2024). "Moreover, IL-1R2 mRNA levels in GCtissues and most GC cells were higher than those in para-cancer tissues and GES1human gastric mucosal epithelial cells." (PMID 33704402, 2021). "Therefore, IL-1R2 is a potential clinical biomarker for human cancer,and a potential new therapeutic target for the treatment of cancer." (PMID 33704402, 2021).
cancer (continued). "Therefore, inhibition ofIL-1 signal transduction is an important therapeutic approach for both cancer andautoimmune diseases, and IL-1R2 caninhibit IL-1 signal transduction." (PMID 33704402, 2021). "IL-1R2 mRNA levelswere higher in GC tissues than in para-cancer tissues(P=0.0191)." (PMID 33704402, 2021). "Most of the genes in the 9-gene classifier (ITGB1, EPHA2, IL1R2) are involved in the migration, immune pathways, adhesion and metastasis of PDAC or other cancers, that are specifically associated with the developmental events and signaling in the progression of cancer." (PMID 33133160, 2020). "Furthermore, the prognostic significance of IL-1R2 is evident in other cancers." (PMID 41415279, 2025). "We found that compared to CTNNB1 WT carcinomas, samples harboring CTNNB1 mutations showed significantly decreased levels of IL1A (p-value = 0.045), IL1B (p-value = 0.12), and caspase 1 (p-value = 0.037), while demonstrating similar IL1R1 and IL1R2 expression levels." (PMID 41227323, 2025). "Moreover, targeting IL1R2 using neutralising antagonists has already been shown to inhibit cancer cell growth, invasion, and chemoresistance in vitro, and might be considered an approach to overcome resistance in gas plasma oncology in the future." (PMID 37460712, 2023). "The detailed mechanisms of action of CRTAC1, HRG, and IL1R2 in cancer progression are not yet fully established." (PMID 40517318, 2025). "These target genes include cancer stemness genes (e.g., sex-determining region Y-box 9 (SOX9), fibroblast growth factor 19 (FGF19), and SOX2), cytokines, and their receptor genes (e.g., interleukin-8 (IL-8) and IL-1 receptor, type II (IL-1R2))." (PMID 32859041, 2020). "However, genetic analyses in mouse or humans formally proving the actual role of IL-1R2 in cancer are still lacking." (PMID 35211118, 2022). "Similarly IL1R2, which has higher expression in our metastatic samples, is a mock receptor of IL1R that regulates immune response through competitive inhibition, and has an important role in cancer progression." (PMID 32850445, 2020). "Since cancer cells of epithelial origin can express IL-1R2, it is possible that in our case cetuximab/EGFR inhibition may be inducing the release of IL-1β as well as IL-1α but we are unable to detect IL-1β due to rapid binding by sIL-1R2." (PMID 30890189, 2019).
infection (40 papers, 2009 to 2026). The state of being infected such as from the introduction of a foreign agent such as serum, vaccine, antigenic substance or organism. "The significant increase in the frequency of MO exhibiting reduced HLA-DR expression and elevated IL-1R2 levels in infected patients (compared to healthy controls) underscores the potential of these markers as indicators of infection severity." (PMID 39519183, 2024). "Since all the patients included in the study had a fever, we can infer the generalized increase in MO IL-1R2 expression level to be a common phenomenon that intervenes to counteract the biological activity of IL-1, even in mild infections." (PMID 39519183, 2024). "In P. leopardus, the expression of IL1R1b and IL1R2 were significantly upregulated at 6–12 h post-infection." (PMID 39450165, 2024). "Interleukins (IL-1β, 6, 8, 11, 12β) and interleukin receptors (IL-1R2) were up-regulated after Aeromonas hydrophila infection, which indicated that the sturgeon employed these interleukins to defense against the infection." (PMID 30560883, 2018). "The genes that were suggestive for association with PTB in fetal (IL1A, IL4 and MMP8) and maternal samples (IL-1R2 and IL-6R) in both the MoBa and Cenn studies were mainly infection and inflammation genes (sector D)." (PMID 20140262, 2010). "Importantly, the expression of membrane-associated IL-1R2 and MS4A4A in these circulating cells correlates with clinical severity markers (e.g., SOFA score, creatinine, cytokine storm), reflecting the infection’s poor prognosis." (PMID 41293423, 2025). "In addition, MO play various roles during the response to infection that are reflected in the modulation of functional cell surface markers such as HLA-DR and interleukin-1 receptor type 2 (IL-1R2, also known as CD121b)." (PMID 39519183, 2024). "Infection led to robust induction of chemokine and interleukin genes, including Il1b, Il6, Ccl2, Ccl3, Ccl4, Ccl7, Cxcl1, Cxcl2, Cxcl5, Cxcl9, and Cxcl10, and related receptor genes, including Ccr1, Ccr4, Ccr5, Ccr5, Ccr7, Cxcr2, Cxcr5, Il1r2, and Il1rn." (PMID 35487885, 2022). "Similarly, the induction of interleukin-1 receptor type 2 in the network of novel_circ_0001907/novel_127/interleukin-1 receptor type 2 was observed after infection." (PMID 33552082, 2020). "Indeed, anti-inflammatory genes exhibited a considerable presence in the infection setting; the IL-10 family of genes important for wound healing and repair (IL1r2, IL1r1, IL-24, IL-19, IL-22) were elevated >2- to 60-fold, although IL-10 itself remained unchanged." (PMID 40586608, 2025). "Similarly, as serum IL-1R2 increases during infection, vaccination in the peri-infection period could blunt the response." (PMID 38329807, 2024). "Therefore, we speculated that the expressions of TLR5 and IL1R2 transcripts were increased under the infection of C. irritans and might be crucial for the innate immune response." (PMID 33281881, 2020). "Integration with RNA-seq data revealed key genes (IL1R2, RBM34, EDEM3, and MZB1) potentially critical in early infection." (PMID 42087228, 2026). "In particular, up-regulation of IL-1R2 was associated with reduced production of IL-6 and ROS after stimulation with LPS, suggesting IL-1R2 contributes to the behavior of monocytes, which act as Trojan horses rather than bactericidal effector cells in this infection." (PMID 35211118, 2022). "Our results indicate that the expression of IL6, IL12B, IL1R2, IL23R, IL12RB1 and IL12RB2 increased after DTMUV infection." (PMID 35585616, 2022). "The elevated expression of IL1R2 gene in COVID19-ACEi and COVID19-ARB was positively correlated with the infection markers of immune cells." (PMID 36817759, 2022). "While IL1R2, IL23R, IL1R1, IL-10, and CCL24 were highly upregulated upon infection of THP-1 macrophages, their expression was barely affected upon infection of primary macrophages." (PMID 34276658, 2021).
infection (continued). "At these conditions only one gene was detected as significantly up-regulated after infection, NLRP2, and four genes were down-regulated (ALDH3A1, CXCL8, IL1R2, KRT15)." (PMID 34785679, 2021). "Most of the genes for chemokines/chemokine receptors (CCR2, CCR6, CCR7, CSF2RB, CX3CR1 and CXCR4) and cytokines/cytokines receptors (IL1R2, IL8, IL18, IL20RA and IL22RA2) were down-regulated after infection by vvIBDV at 3 dpi." (PMID 33110122, 2020). "Only one of our ChIP targets, IL1R2, confirmed enrichment of Smad4-containing complexes on their promoter after TGF-β activation or MP12 infection." (PMID 29408900, 2018). "Eight genes (NCF4, CD14, IL17D, CD1D, CD163, IL1R2, TLR9, and TLR2) with different expression in each infection group were selected for qPCR analysis." (PMID 25906258, 2015). "The mRNA expression of IL1R2 and TNFRSF1B was increased by 4- and 2-fold, respectively, in WT mice at day 8 after infection." (PMID 24750819, 2014). "qPCR analysis demonstrated that for genes that were affected either by infection challenge (e.g. AGR2, G6PC, RETNLB) or diet (e.g. IL1R2, CD3G, ADH1C), gene expression levels of the microarray were verified." (PMID 21698235, 2011). "Notably, the expression of IL1R2 was down-regulated in mutant-infected cells compared to WT-infected cells, while IL1RAP expression was slightly up-regulated by the mutant infection." (PMID 37513744, 2023). "The late emergence of State 6, marked by apoptotic signaling genes (THBS1, IL1R2, S100A8), suggested that ASFV may eventually trigger cell death in heavily infected macrophages, potentially contributing to the cytopathic effects observed in advanced infection." (PMID 40723441, 2025). "Furthermore, the involvement of up-regulated IL7 and IL1R2 in cytokine-cytokine receptor interaction pathway revealed in this study, may be involved in the induction of the inflammatory response against ETEC-F4ac infection." (PMID 32174961, 2020).
immune dysfunction (6 papers, 2018 to 2025). "IL1R2 is an anti-inflammatory antagonist that can prevent immune disorders and systemic inflammation caused by IL1." (PMID 39682511, 2024). "This IL-1R2+ Monocytes subset exhibits hallmarks of immune dysfunction, including low expression of HLA-DR and high levels of macrophage markers (MS4A4A, CD63) and immune checkpoints." (PMID 41293423, 2025). "DEGs that enriched to “immune system diseases” played critical roles in cell-matrix communication (THY1, LVRN, LUM, TIMP3, SPOCK1, LGALS3BP, FAT2, and SERPINE2) as well as inflammation (IL1R2, CD22, PTGES, TNFSF10, IL2RB, C3, SERPING1, and IL-17RE)." (PMID 30131724, 2018).
bacterial infection (4 papers, 2014 to 2024). "The same study showed that the upmodulation of MO IL-1R2 concomitantly with the downmodulation of MO HLA-DR indicated a dysregulated immune response to bacterial infection and a negative prognosis." (PMID 39519183, 2024). "The relative MoDC vs. Mo/MP signature encompasses additional genes that participate in “migration of cells” (p = 10−2.3, with S1PR3, CCL17, and SLC2A1), “bacterial infection” (p = 10−3.2, with CD1B, CD209, and FCGR2B), and “synthesis of nitric oxide” (10−2.5, with PLAU, IL1R2, and NOS2)." (PMID 26150816, 2015).
infectious disease (3 papers, 2010 to 2024). A disorder directly resulting from the presence and activity of a microbial, viral, or parasitic agent in humans. "Among the 24 differentially transcripts identified here in acute phase, the abundance of IL1R2 transcript displayed the most important expression in acutely aged patients with infectious diseases." (PMID 20716329, 2010). "Further studies may be warranted to confirm the utility of MO HLA-DR and MO IL-1R2 modulation in larger populations of patients with infectious diseases in relation to the presence or absence of an underlying (severe) disease." (PMID 39519183, 2024).
IL1R2 also shares sentences with these, for which no sentence is quoted: rheumatoid arthritis (5 papers); Parkinson disease (4); Dengue (3); glioblastoma (3); pancreatic ductal adenocarcinoma (3); acute respiratory distress syndrome (2); allergic asthma (2); amoebiasis (2); cardiovascular disease (2); heart failure (2); infarction (2); influenza (2); multiple sclerosis (2); osteosarcoma (2); periodontitis (2); septic shock (2); acute coronary syndrome (1); acute myeloid leukemia (1); age-related hearing impairment (1); age-related macular degeneration (1); Anxiety (1); autism (1); autoimmune myocarditis (1); bacterial sepsis (1); benign prostatic hyperplasia (1); cervical intraepithelial neoplasia (1); chronic kidney disease (1); chronic obstructive pulmonary disease (1); Cognitive impairment (1); cryopyrin-associated periodic syndrome (1).
A further 41 diseases each share a sentence with IL1R2 in 1 paper.